IRS1 (insulin receptor substrate 1)
Diseases named in the same sentence as IRS1 in open-access papers (continued):
Sharing a sentence is not in itself a finding about the gene and the disease.
cancer (continued). "On the other hand, IRS1 also plays prominent roles in human malignancy and is activated in various human cancers." (PMID 31619254, 2019). "NGF stimulation of insulin pathway via IRS1 transactivation has been previously reported in cancer cells, and occurs upon IRS1 recruitment by the NGF receptor TrkA." (PMID 29736736, 2019). "Expression of IRS1 can be directly activated by β-catenin, and IRS1 is highly expressed in many cancers with constitutive stabilization of β-catenin." (PMID 29749571, 2018). "IRS-1/2 are also ubiquitously expressed in many types of cancer, and suggested to have roles in cancer initiation and progression." (PMID 30338032, 2018). "Theyshowed that miR-126 prevented cell cycle progression inbreast cancer cells via targeting IRS-1 at 3'-UTR." (PMID 29633591, 2018). "MiR-126-enriched exosomes were shown to be transported into recipient cancer cells, where they regulated the downstream targets IRS1 and VEGF, inhibiting cell growth and transformation." (PMID 29127370, 2017). "Influence of NE on BeWo indicated that akin to the report on cancer cells, exogenous NE leads to a significant degradation of IRS1 protein." (PMID 28659928, 2017). "In these cancers, MiR-7 targets several proto-oncogenes, such as insulin receptor substrate 1 (IRS1), epidermal growth factor receptor (EGFR), and p21 protein (Cdc42/Rac)-activated kinase 1 (PAK1)." (PMID 28239300, 2017). "In this instance, it was determined that exogenous NE released by degranulation was absorbed by surrounding cancer cells where its enzymatic activity led to the degradation of a key regulatory molecule, IRS1." (PMID 28659928, 2017). "Seven pathways showed a significant enrichment including “IRS1 Target Genes” and different cancer traits." (PMID 28387357, 2017). "The phosphoprotein phosphatase function of PTEN has been linked to cancer signalling via dephosphorylation of protein targets such as focal adhesion kinase (FAK), insulin receptor substrate 1 (IRS-1), c-SRC or PTEN itself, all of which regulate tumorigenesis." (PMID 28082369, 2017). "The top pathways enriched among the identified CpGs included the “IRS1 target genes” and several pathways in cancer diseases." (PMID 28387357, 2017). "This is particularly exciting as the oncogenic protein IRS‐1 is over‐expressed in a wide range of cancers." (PMID 27304907, 2016). "Silencing of TNS2 promotes the activation of IRS1, Akt, and Mek, and enhances cancer cell tumorigenicities." (PMID 27203214, 2016). "In various cancer cells, overexpression/knockdown experiments indicate that IRS-1/2 promotes cell proliferation, survival, migration, and/or transformation." (PMID 26074875, 2015). "The insulin receptor substrate-1 (IRS-1), previously known as a major docking protein for both the type 1 insulin-like growth factor receptor and the insulin receptor in cancer cell growth and proliferation signaling, was also a validated target of miR-145-5p." (PMID 25888956, 2015). "We also identified overexpression of scaffolding proteins that are traditionally involved in the AKT/mTOR pathway including IRS1, RICTOR, and GAB2, which have been implicated as oncogenic contributors in other cancer types." (PMID 25999352, 2015). "Akt activation promotes signaling in the IGF-1R/IRS-1 axis, which contributes to the dysregulation of NFκB and, ultimately, cancer cell growth." (PMID 25533015, 2014). "The SNP IRS1 rs2943641 also interacted with carbohydrate intake and incident T2D in a sex-specific fashion in the Malmo Diet and Cancer Cohort." (PMID 24929251, 2014). "IRS1 has been shown to be involved in cancer progression and metastasis by mediating proliferative and anti-apoptotic functions of the INSR and IGF1R signaling." (PMID 23818951, 2013). "We then collected 27 cell lines, including four cancer cell lines with the highest mRNA expression levels, and checked for the expression of IRS1, IRS2 and IRS4 proteins by Western blotting." (PMID 24039912, 2013).
cancer (continued). "The biological relevance of the aberrantly methylated and expressed genes was cancer process, including IRS1 that is related to transformation, and collagen-related genes such as COL4A1, COL4A2 and COL6A3." (PMID 23818951, 2013). "In contrast, when IRS1 expression is experimentally decreased, cancer cells lose their transformed phenotype." (PMID 23818951, 2013). "It is also well known that endogenous IRS1 is overexpressed and constitutively activated in a variety of human cancers." (PMID 22558377, 2012). "We investigated expression, localization and pathologic correlations of IRS1 in cancer-uninvolved colonic epithelium, primary CRCs with paired liver metastases and in vitro polarizing Caco2 and HT29 cells." (PMID 22558377, 2012). "A decreased expression of the IGF-IR and downstream signaling proteins such as PI3K, PY99, Akt and MAPK IRS-1 inhibits events in cancer." (PMID 22859258, 2012). "Expression of miR-126 is decreased in various cancer cells, and it has previously been regarded as a cell growth suppressor that acts on IRS-1, HOXA9 and p85β." (PMID 21464990, 2011). "Several growth factor/hormone signaling pathways that are associated with cancer including fibroblast growth factor (FGF), epidermal growth factor (EGF) and insulin can modulate IRS-1 and IRS-2 expression levels." (PMID 19534786, 2009). "To investigate the effect of P-LAP/IRAP transfection on GLUT4, IR, and IRS-1 expressions in carcinoma cells, we overexpressed P-LAP/IRAP in A-MEC cells (A-MEC-LAP)." (PMID 17233921, 2007). "Additionally, the modification of insulin receptor substrate 1 (IRS1) by lactylation enhances its stability and activity, thereby promoting downstream signaling pathways that facilitate cancer cell proliferation and metastasis." (PMID 40867622, 2025). "Additionally, the discovery of the molecular link between PYCR1 and IRS1 provides a valuable framework for understanding metabolic and epigenetic alterations in cancer cells." (PMID 39422696, 2024). "In MCF-7, ZR75 and 4T1 BC cells, as well as in patient-derived Cancer-Associated Fibroblasts, the pharmacological inhibition of RAGE as well as its genetic depletion interfered with Insulin-induced activation of the oncogenic pathway IR/IRS1/AKT/CD1." (PMID 37461077, 2023). "Cancer cells have been found to avoid apoptosis and choose cellular pathways associated with proliferation, motility, adhesion, and migration, where the overexpression of PTK2 and IRS1 proteins plays a role in survival." (PMID 38202644, 2023). "Similarly, hsa-miR-3148 and hsa-miR-3133, which were upregulated in Cancer and located in the central portion of the miRNA-gene network, were also predicted to target IRS1." (PMID 37762604, 2023). "In addition, depletion of IRS-2 significantly diminished tumor growth and metastasis in various organs of mice, thus indicating that IRS-1/2 can serve as a positive regulator of cancer progression." (PMID 37894751, 2023). "The discovery of IRS1 condensates as signal hubs for the PI3K-PKB pathway may also have impacts on other diseases such as cancer." (PMID 35790738, 2022). "The most significant signal, which passed genome-wise significance (rs5839171, Pcorrected = 1.98 × 10−8, Pperm = 3.30 × 10−8), is downstream of the Insulin receptor substrate 1 gene (IRS1) and miR-5702, a microRNA involved in cellular proliferation and cancer risk." (PMID 36324510, 2022). "IRS-1 disruptive effect on cell growth and DNA repair and replication might explain the mir-126 implication in cancer development and progression." (PMID 34199293, 2021). "In addition to the regulatory effect on the insulin signaling pathway, the miR-126/IRS-1 axis is involved in cancer pathogenesis." (PMID 34199293, 2021).
cancer (continued). "Pro-tumoral effects related evidence includes secreting pro-tumoral chemokines like myeloid growth factor granulocyte-colony stimulating factor (G-CSF) to promote cancer progression, suppressing T-cell mediated anti-tumor response and mediating degradation of IRS1 to boost cancer cell proliferation." (PMID 32518520, 2020). "Sincethese receptors induce cell proliferation, survival and migration, it was suggestedthat IRS1 may be involved in the development of cancer and metastasis." (PMID 30807634, 2019). "Many IRS1/ERK/AKT pathway regulators like IRS1, PI3K, PTEN, and AKT are typically mutated or dysregulated in cancer, so it is plausible that miR-30a downregulation may also contribute to not only chemoresistance but also tumorigenesis." (PMID 30770779, 2019). "Our results revealed for the first time that Axl binds to and phosphorylates TNS2 and that Axl/TNS2/IRS-1 cross-talk may potentially play a critical role in glucose metabolism of cancer cells." (PMID 30419905, 2018). "Other SHP2 cancer mutants show a similar trend in response to p-IRS-1 peptide." (PMID 30375388, 2018). "Elevated levels of IRS1 have been reported to contribute to cancer development and progression." (PMID 30594912, 2018). "According toour findings, overexpression of miR-126 may lead todownregulation of IRS-1 and subsequently formation ofglioma cancer stem cell." (PMID 29633591, 2018). "The two key enzymes of aerobic glycolysis (Glut4 and PDK1) were found to be up-regulated by Axl/TNS2/IRS-1 cross-talk and may play a critical role in glucose metabolism of cancer cells." (PMID 30419905, 2018). "These evidences clearly suggest IRS-1/2 as positive regulators of cancer features." (PMID 30338032, 2018). "The Axl/TNS2/IRS-1 cross-talk may further potentially play a critical role in glucose metabolism of cancer cells." (PMID 30419905, 2018). "Recently, the miR-126 that is known to regulate angiogenesis has been found to control cancer metabolism by targeting the insulin receptor substrate-1 (IRS1).39, 71 IRS1 is an adaptor proteins involved in signaling via insulin receptor (IR) and insulin-like growth factor I receptor (IGF-IR)." (PMID 28104913, 2017). "Likewise, carriers of 11 SNPs in the IRS1 and AKT1/2 genes (signaling pathway–related genetic variants) had different associations with CRC risk between strata, and the proportion of the SNP–cancer association explained by traits varied from 30% to 50%." (PMID 29023587, 2017). "Roles of IRS-1/2 in cancer development may be dependent on tissues, oncogenic stimulations, and/or environmental factors." (PMID 26074875, 2015). "Many studies have shown roles for IRS-1/2 in cancer development." (PMID 26074875, 2015). "High expression levels of IRS-1/2 are reported in various types of cancer cells." (PMID 26074875, 2015). "Numerous reviews on the role of the IGF-1R/IRS-1 axis and its role in cancer are available." (PMID 25533015, 2014). "Dysregulation of IRS-1 and -2 has been found in many types of cancer." (PMID 25628647, 2014). "Transgenic mouse models have provided important information regarding IRS-1 function in cancer." (PMID 19534786, 2009). "However, IRS-1 is also ubiquitously expressed in cancer cells." (PMID 36245982, 2022). "These include insulin receptor substrates 1–4 (IRS1–4), and Src homology and collagen domain protein (Shc), which further activate several signaling pathways, including two of the most common dysregulated signaling pathways in cancer and DM: phosphoinositide 3-kinase (PI3K)-AKT and RAS-RAF-MAPK/ERK." (PMID 31847392, 2019).
cancer (continued). "In addition, miR-1225-5p may be a potential target in cancer therapy since it regulates IRS1 and consequent β-catenin pathway, a frequent and crucial signaling event associated with malignant transformation." (PMID 26684358, 2016). "Thus our systematic SPPS‐based approach towards the SAR analysis of this NRPS‐derived linear peptide has allowed the identification of a new and promising lead for use in the design of anti‐cancer therapeutics, and as a tool to study the role of IRS‐1 expression and F‐actin aggregation." (PMID 27304907, 2016). "Thus, the ability of SRA to induce IR protein expression and increase downstream phosphorylations of IRS-1 and Akt in response to insulin may occur in these and possibly other cancers." (PMID 24743795, 2014). "Moreover, IRS-1 is associated with CRC and up-regulated in cancer cell lines." (PMID 24312276, 2013). "These may be the reasons why the expression levels of IRS-1 increase in some types of cancers." (PMID 22788551, 2012). "Thus, there is a complex relationship between IRS-1, ROS, autophagy, and cancer." (PMID 22788551, 2012). "In light of these findings, the recent suggestion that IRS-1 should be considered as a biomarker for IGF-IR activity in cancers susceptible to IGF-IR targeting should be viewed with a degree of caution, especially in cancer types that also express erbB receptors and their ligands." (PMID 21939528, 2011). "MiR-126 alters the biological functions of some genes such as PI3K, EGFL7, HOXA9, sKRAS, CRK, ADAM9, IRS-1, SOX-2, SLC7A5, and VEGF, as well as involves in inflammation, cell migration, angiogenesis, recurrence of cancer, and metastasis." (PMID 38445462, 2024). "Expression of IRS1 and POU2AF1 in MM cell lines extracted from the Cancer Cell Line Encyclopedia and the pan cancer proteomic map46 is highly correlated with genetic dependency." (PMID 38942927, 2024). "IRS1- and IRS2-induced signaling is highly modulated during many cancer processes, such as cell motility, metastasis, and cell proliferation." (PMID 36975518, 2023). "In this paper, we collected data about the molecular mechanisms that explain the relevance of IRS4 in the development of cancer and identify IRS4 differences that distinguish it from IRS1 and IRS2." (PMID 37760618, 2023). "While we used NEO1 as an example, several other genes known to have roles in cancer proliferation and various pathway cascades were identified within these shared compartments, including EPS8, FAM92A, IRS1, and SETBP1." (PMID 37016431, 2023). "The main pathways enriched at the identified CpG loci include “insulin receptor substrate 1 (IRS1) target genes” and several cancer pathways." (PMID 36397166, 2022). "Among all IRSs, IRS-1 and IRS-2 are ubiquitously expressed with high expression in various cancer cell lines." (PMID 33991522, 2021). "Affected genes included FGFR1, IRS1, CLDN4, GRB7, and VCAN, while EZR and MYC were commonly affected in at least four out of five progression stages of the selected cancer levels." (PMID 34069906, 2021). "It is likely that TRAF4 and Nedd4 differentially regulate IRS-1 and IRS-2 ubiquitination and subsequent IGF-1 signaling in cancer cells." (PMID 33991522, 2021). "IRS-1 is one of the central mediators in transmitting signals from IGF-IR receptors via the PI3K/AKT pathway and it is commonly overexpressed in cancer." (PMID 34443299, 2021). "Due to the dysregulation of upstream tumor suppressors or oncogenes, such as PTEN, TSC1/2, PI3K, or IRS1, AKT/mTOR signaling is frequently activated in various cancers." (PMID 33204686, 2020). "IRS‐1, a key molecule in signal transduction between the insulin receptor and PI3K, was demonstrated to be a target gene of miR‐126 in different cancers." (PMID 31115969, 2019).
cancer (continued). "For example, miR-126 was reversibly expressed following asbestos exposure, while its irreversible downregulation resulted in the activation of the IRS1/PI3K/AKT pathway, which is a frequent event in human cancers as it plays a key role in cancer progression." (PMID 31850200, 2019). "Other reported targets of the miR-23a, whose suppression facilitated the cancer cell migration and invasion, include XIAP, metastasis suppressor protein 1 (MTSS1), insulin receptor substrate 1 (IRS-1), Sprouty homolog 2 (SPRY2), and PTEN." (PMID 30577536, 2018). "The results of our present study suggest that knockdown of Axl expression reduces glucose uptake and that Axl is related to high expression of glucose metabolism molecules, IRS-1, Glut4 and PDK1 in cancer tissues." (PMID 30419905, 2018). "The expression levels of TNS2, Axl, IRS-1, PDK1 and Glut4 in human cancer cells were measured by Western blot and/or IP-Western blot assays." (PMID 30419905, 2018). "Treatment of cells with fulvestrant significantly inhibits ER-α dependent IGF-1R, phospho-IRS-1 and PDZK1 pathways regulating cancer cell invasion, survival, metastasis, angiogenesis and proliferation." (PMID 29787591, 2018). "As a result, miR-145-induced IRS1 reduction decreases phosphorylation of AKT and sustains FOXO1 activity to suppress cancer cell growth." (PMID 27999212, 2017). "Liver-specific Irs1-knockout (LIrs1KO) mice exhibited suppression of DEN-induced HCC development, accompanied by reduced cancer cell proliferative activity and reduced activation of Akt." (PMID 28710407, 2017). "On the other hand, IRS-1 is a downstream target of β-catenin, which regulates IRS-1 expression and localization controlling cancer initiation, self-renewal, and differentiation processes." (PMID 28275367, 2017). "To date, it has been well established that miR-7 directly targets many oncogenic factors and is involved into multiple cancer-related signalling pathways, including EGFR, IRS-1/2, Raf1, Pak1, Ack1, PA28-gamma, IGF1R, PIK3CD and mTOR32–38." (PMID 28710406, 2017). "Some studies have revealed that miR-126-3p inhibits cancer growth directly by targeting Sox2, p85β (PIK3R2), IRS1, VEGF and other genes." (PMID 27191494, 2016). "In cancer cells, Akt inhibits the activation of the Raf-MEK-ERK pathway and mTORC1 inhibition results in hyperactive RTK/IRS-1/PI3K pathway increasing the signal towards both, the mTORC2 and the Ras-Raf1-MEK1/2-ERK pathway." (PMID 25880554, 2015). "Enriched genes also included factors involved in cancer pathways and PI3K/AKT signalling, including IRS1, BCL2, TGFB3 and FGF18." (PMID 26698305, 2015). "Taken together, many studies indicate that IRS-1 and IRS-2 play redundant roles in cancer development, but some reports clearly show their distinct roles: IRS-1 tends to promote cancer proliferation whereas IRS-2 preferentially promotes cell migration." (PMID 26074875, 2015). "Analysis of data from The Cancer Genome Atlas (TCGA) using the cBIO portal across most cancer types shows genomic alterations in IGF ligands (IGF1, 2), receptors (IGF1R, IGF2R), binding proteins (IGFBP1–6), and IRSs (IRS1, 2, 4); this representing 18 genes." (PMID 25964777, 2015). "We find that several human cancers express higher TRB3 and phosphorylated insulin receptor substrate 1, which correlates negatively with patient's prognosis." (PMID 26268733, 2015). "Next, we determined if the protein interaction between IRS-1 and RAD51 in our cancer cells was modified after IGF-1Rki treatment using immunoprecipitation." (PMID 26510816, 2015). "In cancer cells, IGF-1R activates IRS-1 by stimulating several intracellular signaling proteins such as PI3K and Akt kinase." (PMID 24970012, 2014). "Furthermore, a recent study reported that treatment with an mTOR inhibitor (WAY-129327) decreased endometrial proliferation, whereas mTOR activation was followed by loss of negative feedback to insulin receptor substrate-1 (IRS-1) during the early stages of cancer development." (PMID 23620761, 2013).